CD4 (CD4 molecule)
Diseases named in the same sentence as CD4 in open-access papers (continued):
Sharing a sentence is not in itself a finding about the gene and the disease.
tumor (continued). "Unlike CD4+ T cells, such cells, if transformed by proviral integration, would not be good targets for HIV superinfection and killing, allowing even rare infected cells to grow into a tumor." (PMID 33318172, 2020). "Moreover, SNAI1 expression was negative closely related with infiltrating levels of tumor purity and B cell in COAD, and positively closely related with CD4+T cells, macrophages, dendritic cells, and neutrophils in COAD." (PMID 32833672, 2020). "Although the GBM microenvironment was infiltrated with CD4+ T cells, CD8+ T cells, and NK cells, the proportions of nonfunctional immune cell subpopulations and Tregs increased, while whole T cell numbers were reduced at the tumor site." (PMID 32457755, 2020). "In the long-term experiment, a slight decrease in T-helper cells (CD3+/CD4+/CD8−) and a slight increase in cytotoxic T cells (CD3+/CD4−/CD8+) in peripheral blood was observed in the tumor mice compared to the normal weight mice without tumor cell injection." (PMID 33244094, 2020). "Similarly, treatment did not affect tumor residing or peripheral CD3+, CD4+, CD8+ T-cells or their ratio in tumor or blood." (PMID 32681091, 2020). "CD4+ T helper cells can assist in the activation of naive CD8+ T cells and can help to eliminate major histocompatibility antigen class II (MHC-II)-negative tumor cells." (PMID 32571262, 2020). "The analysis of the distribution of the tumour-infiltrating immune cell subsets within the TIL-gated population was next performed and showed no significant changes in the percentage of CD3+, CD4+ or CD8+ T lymphocytes, or NK cells between treated and untreated animals." (PMID 31748740, 2020). "In T cells, the ability of TLR3 signaling to obviate CD4- or APC-mediated costimulation and formation of memory T cells is a helpful feature for the design of cancer vaccines because costimulatory signals are absent in a tumor microenvironment." (PMID 32012718, 2020). "With or without RCT treatment, the CD4+/CD8+ ratio (around 1–1.5/3) was in favor of the CD8+ lymphocytes in the GL261-wt as well as in GL261-Ang2 tumors, whereas this ratio was opposite in the blood and in the spleen of tumor-bearing mice." (PMID 33266255, 2020). "Similarly, RBPJL‐overexpressing group exhibited greater infiltration of CD4+ and CD8+ T cells and tumor inhibition than the IgG group in the absence of toripalimab." (PMID 32994998, 2020). "In the present study, we found that YPF could enhance the population of CD4+ T cells, but had no obvious influence in the percentage of CD8+ T cells in tumor tissues." (PMID 31780946, 2019). "To dissect whether Fas signaling is related to TH9 cells in tumor-bearing mice, we injected B16F10 cells intravenously into WT mice and analyzed Il9 mRNA levels in Fas-positive and Fas-negative CD4+ T cells." (PMID 31266950, 2019). "Furthermore, tumor-specific increases in the percentages of Tim-3 and Lag-3 Tregs, CD8+ and non-Treg CD4+ T cells were observed, confirming that part of the tumor-infiltrating T cells has been activated." (PMID 31481117, 2019). "In addition, depletion of CD4 and CD8 T cells by Ab treatment in piTRL-treated mice that were cured from the 1st transplanted tumor failed to protect from the 2nd transplanted cancer." (PMID 31412934, 2019). "Interestingly, the infiltration of CD4+ and CD8+ T-cells, but not of NK cells, into the tumor mass depended strongly on BATF3-dependent DCs." (PMID 31188899, 2019). "Notably, no significant increase in CD4+ and CD8+ tumor infiltrating T cells was observed between the PD-1 Ab-treated and isotype control-treated mice bearing LDH-A expressing B16-F10 tumors." (PMID 30934955, 2019). "Because CD4+ T cells can alter the tumor microenvironment and facilitate CD8+ T cell trafficking and function at the tumor site, our finding that CD4+ T cells are vital for the recruitment of CD8+ T cells to the tumor site is perhaps not unexpected." (PMID 31112530, 2019).
tumor (continued). "Both the CD4+ and CD8+ T-cells were almost completely absent and the percentage of CD19+ B-cells decreased from 50% to 10% of CD45+ living singlets in the spleen of the 4T1 tumor bearing mice." (PMID 31881770, 2019). "In addition, flow cytometric analysis for CD4 and CD8 T-cell markers revealed that MPL tumours have a slightly different spectrum of tumour immunophenotypes with more CD4−CD8− double negative tumours as compared to PLs or dEPLs." (PMID 31332244, 2019). "While there was only a limited effect on the level of CD4+ T cells and no obvious effects on Tregs, there was a significant increase in CD8+ T cells in both injected and contralateral uninjected tumours in virus-treated animals, but not in vehicle-treated controls." (PMID 31399043, 2019). "The overall proportion of T cells in the tumor had no significant increase (CD3+); however, encouragingly, the number of both CD4+ and CD8+ T cells increased, while that of Treg population (CD4+Foxp3+) decreased, reflecting an activation of the adaptive immune response." (PMID 31118418, 2019). "Further studies into the impact of PFRs is warranted to decipher whether tumor-epitopes may indeed be more dependent on PFR tuning, compared with nonself systems, due to the weak sensitivity of the 5T4 CD4+ T-cell response observed here at the clonal level." (PMID 31619516, 2019). "Tumor size (P = .02), histological grade (P = .01), ER status (P < .001), PR status (P < .001), HER-2 expression (P = .004), Ki67 index (P < .001) are also significantly correlated with OS but not age and CD4 expression." (PMID 31852159, 2019). "Furthermore, in tumour bearing mouse AKI models, CD4 depletion does not protect against cisplatin-induced AKI and results in worsening tumour burden." (PMID 31226747, 2019). "The frequency of both T helper 1 and 2 (TH1 and TH2) CD4+ T cells is increased in CLL, and, although there is no clear TH1/TH2 skewing, TH2 expansion correlates with progressive disease, in line with their proposed tumor-supportive role in CLL." (PMID 31484424, 2019). "After NPS treatment, CD4+ and CD8+ Tem cells were no different from pre-treated tumor-bearing rats." (PMID 29533981, 2018). "D-TILs was here defined as numbers of CD4+ cells, with and without FOXP3, and CD8+ lymphocytes per mm2 of tumor determined through 180 multispectral, multicolor immunofluorescence (IF) image cubes (×200 magnification; median of 3 images per case; n = 51 selected CRPC biopsies)." (PMID 30179225, 2018). "Interestingly, we found no significant changes in CD4 populations between the groups, but we found a decrease in CD8 T cells after the triple combination at the primary tumor site." (PMID 30294332, 2018). "It is known that CD4+ T cell help is necessary for an effective CD8+ T cell memory response against non-inflammatory antigens, such as tumor cells and certain pathogens that may not carry sufficient danger signals." (PMID 30073152, 2018). "A previous report had shown oligoclonal expansion of tumor-reactive effector memory T cells in TILs from two clear cell RCC patients, although whether these cells were CD4, CD8 or DP T cells was not specified." (PMID 30534127, 2018). "Although the successful allogeneic transplantation did not induce long-term anti-tumor effects in the mice, the prevention of GVHD by incubating graft cells with the anti-CD4 antibody prolonged their survival significantly thereby opening a time frame for additional treatment options." (PMID 30405611, 2018). "Treatment with the mPD1-Fc-OX40L ARC led to an increase in CD4+ T cell populations in both the tumor and spleen, that were enriched for effector T cells (CD4+CD25−) compared with non-effector/Treg (CD4+CD25+ or CD4+FOXP3+) cells." (PMID 30563566, 2018).
tumor (continued). "While 18 immune cell types showed no good correlation with the analysed tumour stages, the marker enrichment analysis revealed reduced numbers of T cells, CD8+, Th1 as well as CD4+ regulatory T cells and dendritic cells in samples from more advanced HCC patients." (PMID 29599491, 2018). "Similarly, 7 days following radiation there was an increase in non-Treg CD4 cells expressing ICOS in the blood (7.73% vs 3.68%, p<0.0001, n=5/group) and the tumor (62.16% vs 34.04%, p=0.004, n=5/group)." (PMID 30400822, 2018). "In addition, treatment with pIL-12 GET can induce a potent proliferation of memory (CD44+) CD4+ and CD8+ T cells, but not NK cells in the peripheral blood leading to induction of protection from tumor relapse and metastasis." (PMID 30544810, 2018). "Also present were CD4+IL-7Rα+PD-1− and lower numbers of CD8+ IL-7Rα+PD-1−, likely TEM cells trafficking to the tumor site but not responding to antigen." (PMID 30042403, 2018). "Upregulated CD4 and CD40L on CD8 could thus perhaps be a mechanism for CD8 to counterbalance the negative effect of the tumor micro-environment on CD8 activation." (PMID 30534127, 2018). "Furthermore, immunological staining of FOXP3, CD4 and CD8 showed no marked difference in immune cell infiltrate in tumor environment following treatment." (PMID 29492202, 2018). "While T cells were consistently expressed in the other models, most prominent in the i.v. injection of LLC, the immunohistological examination of 3D cell culture model showed CD4+ and CD8+ cells to be almost absent in tumor spheroids built from cells of s.c.-LLC injection tumor." (PMID 30093966, 2018). "Given that CD4+ but not CD8+ T cells appear to have a role in the efficacy of obinutuzumab and R848 combination therapy we investigated whether tumor-specific T cells can be detected early during the course of therapy." (PMID 27890931, 2017). "While CD200-/- mice were cured of tumor growth using conventional chemotherapy with a combination of paclitaxel and anti-VEGF antibody, this treatment was not affected by anti-CD4 or anti-CD8 treatment, and did not lead to development of any immunity to re-challenge with the same tumor." (PMID 28234914, 2017). "Diagnosis is based on detection of CD4+ CD56+, CD123high, TCL-1+, and blood dendritic cell antigen-2/CD303+ blasts, together with the absence of lineage specific antigens on tumour cells." (PMID 28409040, 2017). "This increased frequency of tumour antigen-specific CD8+ TILs from Grail−/− mice was maintained at day 17; however, we did not detect changes in the percentage of Grail−/− CD4+ TILs compared to WT." (PMID 28798332, 2017). "Interestingly, Cbl-b expression was not increased in CD4+ and CD8+ TILs, suggesting a distinct regulation and function of Grail and Cbl-b in tumours." (PMID 28798332, 2017). "We show a decreased ratio of IFNγ+ to FOXP3+ cells in CD4+ TILs lacking HIF-1α, which could further contribute to the observed accelerated tumor growth." (PMID 29136509, 2017). "The proportion of CD4+ cells among CTLA-4+ T cells in non-cancerous mucosa was decreased compared to PBMC HNSCC (51.0 ± 18.8% vs. 69.3 ± 14.6%; p < 0.05), but not compared to tumor tissue." (PMID 28574843, 2017). "In contrast to the low level of tumor T cell infiltrate found in the non-treated mice, five out of six ADI-PEG 20 treated animals had a large number of T cells in their tumors, both CD4+ and CD8+ (data not shown)." (PMID 28938609, 2017). "First, we only analyzed the density of tumor-infiltrating CD8(+) T cells, but did not analyze the densities of CD3(+) T cells and CD4(+) T cells, which may also have prognostic values in GC patients." (PMID 28754154, 2017). "We found that tumor-infiltrating CD4+CCR4+ T cells, but not CD4+CCR2+ T cells, were enriched in GBM tissues, suggesting that CD4+CCR4+ T cells had relatively specific infiltration in GBM." (PMID 29312296, 2017).
tumor (continued). "We also tested the anti-tumor activity of bulk CD19 CAR-T cells containing CD4 T cells and CD8 T cells that were expanded in the presence of Akti and compared them with non-treated cells having the same proportion of CD4, CD8, and CAR subsets." (PMID 28331616, 2017). "Also analyzed were non-tumor draining (brachial, BLN), tumor-draining lymph nodes (inguinal, ILN) and MC32A tumor microenvironment for changes in CD4+ FoxP3+ and proliferative/activated (i.e., Ki67+/CD44+) CD4+FoxP3- and CD8+ effector T cells." (PMID 29088720, 2017). "Moreover, while systemic depletion of CD4+ and CD8+ T cells prevented T cell re-colonization of tumors following Myc de-activation, it does not measurably retard either stromal collapse or tumor regression." (PMID 29195074, 2017). "Tumors are infiltrated by CD4+ and CD8+ lymphocytes and by other leucocytes/macrophages at various degrees depending on the HLA-I positive/negative tumor cell ratio within the heterogeneous tumor mass." (PMID 28264447, 2017). "We demonstrate here that co-transferring less differentiated CD4+ Th1 cells and CD8+ CTLs without lymphodepletion and IL-2 administration enhances complete tumour remission and also results in generation of an endogenous memory response to non-ACT target epitopes." (PMID 29114389, 2017). "However, the levels of PD-1+TIM-3− cells did not increase in CD4+ and CD8+ T cells in tumor tissues as compared to AEM." (PMID 27577071, 2016). "Moreover, L-selectin was not altered on thymic naïve CD4+CD44lo and CD8+CD44lo T cells when compared to non-tumor bearing controls (NTB)." (PMID 27929373, 2016). "It has been suggested that CD4+ T cells may be of limited impact in immunotherapy, since most tumor cells lack expression of MHC class II molecules, and thus are not directly recognized by CD4+ T cells." (PMID 27626487, 2016). "In spleens from mice with actively growing tumor, CD8+ but not CD4+ T cells were virtually absent." (PMID 27959896, 2016). "Interestingly, while tumor bearing alone was shown not to affect CD4+/CD8+ value, CTX treatment significantly increased the CD4+/CD8+ value in the turmor-bearing mice." (PMID 26753518, 2016). "Furthermore the comparable low MHC-I and MHC-II expression levels on the two tumor cell lines rules out improved recognition of B16SLC35A1 by tumor-reactive CD8+ and CD4+ T cells." (PMID 26741508, 2016). "In the CT26 model, tumor-bearing mice treated with anti-CTLA-4 in combination with anti-PD-1 exhibited an increase in the frequency of CD8+ T cells, but not of CD4+ T cells amongst TIL (72% increase in CD8+ T cell frequency relative to control treatment, p<0.01)." (PMID 27610613, 2016). "Additionally, GARP−/+LAP+ CD4+ T cells made IL-10, and not IFN-γ, and levels of IL-10-secreting CD4+ T cells were elevated in LICRC patients, especially with higher tumor staging." (PMID 26885615, 2016). "To this end, we first utilized the RNA-Seq data from sorted tumor-infiltrating cells and generated a reference expression profile for each one of the sorted immune cell populations (CD8+ T cells, NK CD16+ cells, CD4+ T cells, and macrophages) as well as for non-immune CD45– cells (see “Methods”)." (PMID 27855702, 2016). "We also used antibodies specific for CD3, CD4, and CD8 and observed lymphocytic infiltrates; in contrast to what observed with microglia, there were no obvious differences in tumor sections from vaccinated mice compared to tumor sections from mock-vaccinated mice (data not shown)." (PMID 26727970, 2016). "Since combination therapy significantly improved CD4+ non-Treg/Treg and CD8+/Treg ratios as compared to α-CTLA-4 or α-PD-1 monotherapy in tumours, we reasoned that combination therapy could more potently stimulate effector functions of TILs." (PMID 27498556, 2016). "CCR2+ T cells were nearly absent in FoxP3+CD4+ T cell fractions, indicating that HNSCC-circulating aTreg cells may be recruited to the tumor microenvironment by endogenous MCP-1 via binding to CCR4 but not CCR2." (PMID 27177223, 2016).
tumor (continued). "An immune-evasion mechanism suggested is the tumor’s ability to downregulate or express low levels of class-I MHC, hiding its existence from the cellular arm of the immune system, thus not detected by CD4+ T helper cells or CD8+ CTLs." (PMID 26807257, 2016). "Furthermore, these levels of both CD4+CD25+ and CD25+Foxp3+ cells in (rapamycin + SK-TCL-mDC)-treated mice were quite comparable to the levels detected in normal (i.e., not tumor-bearing) mice (i.e., 3.4% and 0.4%, respectively)." (PMID 26426423, 2015). "Frequencies and absolute numbers of SIY-specific T cells were similar between CD4-cre x IKKβfl/fl mice and littermate controls, suggesting similar expansion and survival of SIY-specific CD8+ T cells following tumor exposure regardless of the presence or absence of IKKβ." (PMID 25648675, 2015). "Therefore, it is important to understand the role of CD4+ T cells that are naturally induced in the tumor-bearing host and directly recognize tumors in the absence of APCs, and test whether they can counteract tumor progression and facilitate anti-tumor immune responses in humans." (PMID 26447332, 2015). "CD4 T cells harvested from mice treated with anti-PD-L1 plus anti-LAG-3 or anti-TIM-3 also released IFN-γ when stimulated with 5T33-CIITA cells, but there was no spontaneous or tumor-induced release of IFN-γ, IL-4 and IL-5." (PMID 25614821, 2015). "Another study demonstrated that, in the peripheral blood of PNS patients, the percentage of CD4+ T cells and the ratio of CD4+/CD8+ cells is decreased, leading to a degree of immune function inhibition in patients with PNS, but no clear inhibitory effects on tumor cells cultured in vitro." (PMID 25412252, 2015). "Interestingly, although n24 reacted with the HSC4 tumor cells producing IFN-γ, these CD4 T cells did not lyse the HSC4 cells." (PMID 26538233, 2015). "However, the proportions of CD4, CD8, and CD56 cells are not significantly (P > 0.05) correlated with other clinicopathological parameters, including tumor type, IL-4, and toxicity." (PMID 26515587, 2015). "In the DC:tumor cell co-cultures, addition of TOFA did not; (i) reduce DC lipid levels; (ii) restore DC antigen processing ability; (iii) increase the ability of tumor-exposed DCs to induce allogeneic CD4+ and CD8+ T cell proliferation." (PMID 25886502, 2015). "The capacity of tumor cells (MCF7 and M628) to induce senescence in naïve CD4+ T cells was investigated in the presence or absence of a panel of neutralizing antibodies against IL-10, TGF-β, TCRαβ, PDL-1, and MHC-class II, as well as the IDO inhibitor, 1-methyl-D-tryptophan (1-MT)." (PMID 25231413, 2014). "In contrast to CD4 T cell depletion, which did not result in any long-term survivors, depletion of CD8 T cells resulted in a significantly decreased survival and increased residual tumour outgrowth compared to debulk plus IMQ." (PMID 25518732, 2014). "Further experimental results showed that tumor-activated γδ T cells neither induced the proliferation of CD4+CD25+ Treg cells (n = 3) nor enhanced the apoptosis of CD4+CD25+ Treg cells (n = 3), when cocultured with CD4+CD25+ Treg cells." (PMID 24741609, 2014). "In conclusion, the researcher had proved that the tBregs could transform nonregulatory CD4+ T cells (non-Tregs) to active Tregs through secreting the TGF-β, which in turn inhibited T cells proliferation and increased tumor metastasis." (PMID 24991577, 2014). "Interestingly, no significant reduction was noted in CD4+ T cells, CD8+ T cells or B cells, and an increase in the anti-tumor activity of CD8+ T cells and activated NK cells was noted, making this a promising MDSC targeting agent." (PMID 23508517, 2013). "One possible hypothesis to explain this observation could be that monocytes/macrophages are attracted by the tumor cells to the affected lymph nodes via CCL5 in the absence or relative lack of CD4+ T cells in the blood." (PMID 24244368, 2013).